KMT2B (lysine methyltransferase 2B)
Diseases named in the same sentence as KMT2B in open-access papers (continued):
Sharing a sentence is not in itself a finding about the gene and the disease.
colon cancer (5 papers, 2021 to 2024). "In particular, histone-lysine N-methyltransferase genes KMT2D, KMT2C and KMT2B in bladder, lung and endometrial cancers, whereas the KMT2A is mostly mutated in non-small cell lung cancer and colon cancer." (PMID 34302033, 2021). "Results from the analysis with the non-cancer multi-tissue network and the colon cancer GWAS included the genes KMT2B, PTBP1 and GEN1 (p-values 2.0 × 10− 6, 3.0 × 10− 6 and 3.0 × 10− 6, respectively)." (PMID 39010058, 2024). "In addition, CBX8 recruits KMT2B (lysine methyltransferases 2B) to the LGR5 promoter, which maintains H3K4me3 status to promote LGR5 expression, resulting in increased cancer stemness and decreased chemosensitivity in colon cancer." (PMID 34090418, 2021).
Intellectual disability (5 papers, 2022 to 2025). "Many patients with KMT2B mutations present with an overlapping neurodevelopmental phenotype, and we propose that microcephaly, dysmorphism and intellectual disability should be recognized as core disease features." (PMID 39990802, 2025). "We report the clinical and genetic findings of a series of subjects affected by adult-onset dystonia, hearing loss or intellectual disability carrying rare heterozygous KMT2B variants." (PMID 36483457, 2022). "Moreover, we hypothesized that KMT2B gene duplication might be associated with intellectual disability." (PMID 36959829, 2023). "An adult male with multiple renal and hepatic cysts harbored a similar complex deletion involving PKD1 (MIM: 601313; Family 11), while another participant recruited due to intellectual disability and short stature (Family 14) carried a similar de novo rearrangement involving KMT2B (MIM: 606834)." (PMID 38776926, 2024). "In this clinical and genetic report, we present twelve cases from five unrelated families carrying four rare functionally relevant KMT2B variants who presented with adult-onset dystonia or non-dystonic phenotypes including progressive hearing loss, intellectual disability and short stature." (PMID 36483457, 2022).
cervical cancer (4 papers, 2023 to 2025). A primary or metastatic malignant neoplasm involving the cervix. "KMT2B-mediated tumorigenesis in cervical cancer is conditioned by inducing angiogenesis and modulating the epithelial growth factor pathway, hinting that targeting epithelial growth factor receptors could boost therapeutic efficacy in cervical cancer patients exhibiting high KMT2B expression." (PMID 38791111, 2024). "Evidence has indicated that lysine methyltransferase 2B (KMT2B), a major H3K4 tri-methyltransferase (H3K4me3), contributes to the development of various cancers; however, its role in cervical cancer (CC) is unclear." (PMID 36594087, 2023).
generalized dystonia (4 papers, 2020 to 2025). "KMT2B gene is now recognized as one of the most common causes of early-onset generalized dystonia, accounting for ~10% of cases and representing the most frequent form outside Ashkenazi Jew (AJ) ancestry." (PMID 40584247, 2025). "Mutations in the histone lysine methyltransferase gene KMT2B has been found leading to early onset generalized dystonia in humans." (PMID 36614124, 2022). "Mutations in the lysine methyltransferase 2B (KMT2B) gene have recently been reported to be associated with childhood-onset generalized dystonia." (PMID 32886413, 2020).
liver cancer (4 papers, 2016 to 2024). An epithelial or non-epithelial malignant neoplasm that arises from the liver. "KMT2B is located in the interval of 40 M-50 M on chromosome 19, and it is a gene that affects DNA repair and cell cycle, and at the same time is an important driving gene for liver cancer." (PMID 38704528, 2024).
Parkinsonism (4 papers, 2022 to 2025). Characteristic neurologic anomaly resulting from degeneration of dopamine-generating cells in the substantia nigra, a region of the midbrain, characterized clinically by shaking, rigidity, slowness of movement and difficulty with walking and gait. "Variants in none of the five implicated dystonia genes (TOR1A, SGCE, GNAL, THAP1 and KMT2B) have been reported to cause PD/parkinsonism to date." (PMID 39087914, 2024).
gastric cancer (3 papers, 2023 to 2025). A primary or metastatic malignant neoplasm involving the stomach. "Among other gastric cancer-associated genes, the epigenetic modifier KMT2B was also more frequently mutated in cancers with higher CDX2 expression (12.6% versus 3.2% in cancers with lower CDX2, Fisher’s exact test p = 0.03)." (PMID 39768557, 2024). "The group with SOX2 suppression had higher rates of mutations in many gastric cancer-associated genes such as epigenetic modifiers ARID1A, KMT2D, KMT2C, and KMT2B, as well as higher rates of mutations in genes encoding for receptor tyrosine kinases ERBB4 and FGFR1." (PMID 40149431, 2025). "However, SOX2 suppression may be permissive for a sub-set of gastric cancers with CDX2 induction to acquire mutations in epigenetic modifier genes, including ARID1A, KMT2D, KMT2C, KMT2A, and KMT2B." (PMID 40149431, 2025).
cervical dystonia (2 papers, 2022 to 2024).
epilepsy (2 papers, 2022 to 2024). A brain disorder characterized by episodes of abnormally increased neuronal discharge resulting in transient episodes of sensory or motor neurological dysfunction, or psychic dysfunction. "Pathogenic variants in CACNA1A, KCNA2 and KMT2B were associated with epilepsy; seizures are a known feature of the first two." (PMID 39048885, 2024).
focal dystonia (2 papers, 2022 to 2023). A dystonia that is localized to a specific part of the body. "Moreover, we found evidence for allelic series, including KMT2B-variants with moderate effects and comparatively mild phenotypes such as late-onset focal dystonia." (PMID 37365401, 2023). "The TOR1A, KMT2B, or WASHC5 mutations were identified as causative gene in three patients with childhood-onset focal dystonia." (PMID 35719373, 2022).
gastric adenocarcinoma (2 papers, 2024 to 2025). "Moreover, KMT2B had divergent effects on immunotherapy response, with higher KMT2B expression associated with response in melanoma patients (p = 0.043) and lower KMT2B expression linked to response in stomach adenocarcinoma patients (p = 0.001)." (PMID 40867302, 2025).
hepatocellular carcinoma (2 papers, 2022 to 2025). A malignant tumor that arises from hepatocytes. "Our previous study revealed that KMT2B was recurrently targeted by HBV DNA > 100 times in patients with hepatocellular carcinoma, suggesting that KMT2B is a novel and critical regulator of hepatocellular carcinoma proliferation and metastasis (data not shown)." (PMID 35592651, 2022).
Kabuki syndrome (2 papers, 2021 to 2023). Kabuki syndrome (KS) is a multiple congenital anomaly syndrome characterized by typical facial features, skeletal anomalies, mild to moderate intellectual disability and postnatal growth deficiency. "Using similar methodology, we previously found that comparison of methylation profiles in KMT2B NDD individuals (n = 10) and KMT2D associated Kabuki syndrome individuals (n = 10) to control samples (n = 29) identified 1812 and 89 significant DMPs, respectively." (PMID 37166351, 2023).
Kabuki syndrome type 1 (2 papers, 2023 to 2025). "In other disorders, such as childhood-onset dystonia and Kabuki syndrome type 1, abnormal methylation profiles in the lysine methyl transferase 2B (KMT2B) gene can improve diagnostic accuracy." (PMID 41150803, 2025).
microcephaly (2 papers, 2023 to 2025). A congenital or acquired developmental disorder in which the circumference of the head is smaller than normal for the person's age and sex. "Mutations in MLL2/KMT2B have been commonly associated with early onset generalized dystonia, which is a disorder characterized by sustained muscle contractions causing abnormal, repetitive movements, and in a small number of cases has been associated with ID, facial dysmorphisms and microcephaly." (PMID 36845425, 2023).
non-small cell lung carcinoma (2 papers, 2021 to 2023). A group of at least three distinct histological types of lung cancer, including non-small cell squamous cell carcinoma, adenocarcinoma, and large cell carcinoma. "For instance, in non-small cell lung cancers, KMT2B increased the c-Myc transcription." (PMID 36594087, 2023).
pancreatic carcinoma (2 papers, 2024 to 2025). "Our findings reveal a novel KMT2B/FYN/PI3K/Akt axis through which KMT2B promotes the malignant behaviour of pancreatic cancer." (PMID 40741875, 2025). "HBV DNA integrates in multiple genes including KMT2B in pancreatic cancer." (PMID 40741875, 2025). "In addition to the oncogenic role of KMT2B in other cancers, pancreatic carcinoma displays an amplification in a zone that involves the KMT2B gene." (PMID 38791111, 2024).
Adult onset (1 paper, 2022). Onset of disease manifestations in adulthood, defined here as at the age of 16 years or later. "In this view, KMT2B gene should be considered in patients with adult-onset progressive dystonia involving the upper body part, in particular the larynx and oromandibular region and/or the upper limb." (PMID 36483457, 2022).
Anxiety (1 paper, 2024). Intense feelings of nervousness, tension, or panic often arise in response to interpersonal stresses. "Selective ablation of lysine (K) methyltransferase 2a (Kmt2a), a HMT specific for H3K4, which is linked to active transcription, but not the ortholog Kmt2b, in adult ventral striatum/nucleus accumbens neurons, however, markedly increased anxiety-like behavior in multiple behavioral paradigms." (PMID 36946487, 2024).
asthma (1 paper, 2023). "These four genes, SMARCC1, SETD2, KMT2B, and CHD8, were used to construct a nomogram model for predicting the prognosis of patients with severe asthma." (PMID 37245015, 2023). "The nomogram constructed using the four CRs, SMARCC1, SETD2, KMT2B, and CHD8, may be a useful tool for predicting the prognosis of patients with severe asthma." (PMID 37245015, 2023).
brain cancer (1 paper, 2024). A primary or metastatic malignant neoplasm affecting the brain. "Therefore, more research may identify how alterations of KMT2B and PRC2 in brain cancer and its treatment could potentially trigger AD development." (PMID 39765675, 2024).
brain tumors (1 paper, 2024). "Some of the frequently mutated genes have been rarely reported in brain tumors according to the COSMIC database: EPH2B (67% vs 1.11%), DICER1 (67 vs 1.25%), KMT2B (67% vs 1.46%), ATRX (67% vs 13.95%) as well as several muscular genes (DMD, MYO10, MYO9B, MYH6) (P < .00001, Fischer exact test)." (PMID 39233831, 2024).
cerebral palsy (1 paper, 2025). A group of disorders affecting the development of movement and posture, often accompanied by disturbances of sensation, perception, cognition, and behavior. "Genetic testing becomes invaluable here, as identifying a mutation in the KMT2B gene can confirm the diagnosis, distinguishing it from cerebral palsy and guiding more precise treatment options." (PMID 40303543, 2025).
cognitive decline (1 paper, 2024). "Two of these genes, COX6B1 and KMT2B, are involved in monogenic childhood-onset neurological disorders with cognitive decline and delayed motor or cognitive development." (PMID 38811690, 2024).
Endometrioid carcinomas (1 paper, 2020). "Endometrioid carcinomas, which originate from the same tissue as OCCC, have been shown to frequently harbor mutations in genes such as CTNNB1 (42% of samples), KMT2D (31%), KMT2B (19%), and PIK3R1 (19%)." (PMID 33153119, 2020).
Failure to thrive (1 paper, 2020). Failure to thrive (FTT) refers to a child whose physical growth is substantially below the norm. "A previously undescribed variant, c.4960 T > C (p.Cys1654Arg), was identified in the KMT2B gene in the proband and mother, and this variant was subsequently confirmed in two maternal cousins, one with failure to thrive." (PMID 32546208, 2020). "We describe a family with novel KMT2B mutation with several members with failure to thrive to highlight this non-neurologic, but consequential impact of mutation in this gene." (PMID 32546208, 2020).
glioblastoma (1 paper, 2020). The most malignant astrocytic tumor (WHO grade IV). "A region harboring the KMT2B gene was shown to be amplified in certain pancreatic cancer cells and was frequently translocated in glioblastomas." (PMID 33302406, 2020).
Glutaric Aciduria type 1 (1 paper, 2023). "The genetic dystonias were associated with the following genes: TOR1A, THAP1, SGCE, KMT2B, HPRT1 (Lesch Nyhan disease), PANK2 and GCDH (Glutaric Aciduria type 1)." (PMID 36445406, 2023).
hearing loss (1 paper, 2022). "A further word of caution is necessary concerning the association of KMT2B pathogenic variants with hearing loss as it has only rarely been reported and has been identified only in one of the families shown here, leaving open the possibility of a coincidental association with the KMT2B variant." (PMID 36483457, 2022).
hyperkinesia (1 paper, 2022). "Effective disease‐specific therapies included dopaminergic agents for neurotransmitters disorders, ketogenic diet for glucose transporter deficiency, and deep brain stimulation for SGCE‐, KMT2B‐, and GNAO1‐related hyperkinesia." (PMID 36054588, 2022).
idiopathic dystonia (1 paper, 2021). "Seven (10%) patients had confirmed genetic diagnosis (including THAP1, ADCY5, VPS41, ATXN3, AFG3L2, KMT2B), 12 (18%) had acquired causes and the remainder had idiopathic dystonia." (PMID 34437382, 2021).
juvenile onset dystonia (1 paper, 2021). "P5 additionally presented progressive, juvenile onset dystonia with predominant cranio-cervical involvement and was finally diagnosed with KMT2B-related childhood onset dystonia (Dystonia 28; DYT28) by identification of the novel de-novo c.5697del (p.Thr1900Glnfs*34) KMT2B variant." (PMID 34828254, 2021).
kernicterus (1 paper, 2023). A term used pathologically to describe BILIRUBIN staining of the BASAL GANGLIA; BRAIN STEM; and CEREBELLUM and clinically to describe a syndrome associated with HYPERBILIRUBINEMIA. "Temporal lobe glucose hypometabolism was found in KMT2B, HPRT1 and CP-Kernicterus." (PMID 36445406, 2023).
Kleefstra syndrome (1 paper, 2014). A genetic disorder characterized by intellectual disability, childhood hypotonia, severe expressive speech delay and a distinctive facial appearance with a spectrum of additional clinical features. "The KMT2B recessive variant is the first report of recessive Kleefstra syndrome-like phenotype." (PMID 25405613, 2014).
lymphoproliferative disorders (1 paper, 2020). "Some of these mutations, for example, EZH2, HIST1H1C, and HIST1H1E, KMT2B/MLL2, NOTCH2, CIITA, TANK, and ATM are also reported in other lymphoproliferative disorders." (PMID 35844989, 2020).
memory impairment (1 paper, 2021). "To test this hypothesis, we retrieved and re‐analyzed hippocampal RNA‐seq data from mutant mice that lack the H3K4 methyltransferases Kmt2a or Kmt2b from hippocampal neurons of the adult brain and also display hippocampus‐dependent memory impairment." (PMID 33471428, 2021).
neuroendocrine carcinomas of (1 paper, 2023). "PIK3CA, WNK2, and KMT2B underwent mutations in both the dMMR-like subtype of NECC (50% – 75%) and in NECE (60% – 80%) specimens, while exhibiting infrequent mutational occurrences in publicly available data pertaining to neuroendocrine carcinomas of the lung or bladder (< 10%)." (PMID 37920164, 2023).
prostate carcinoma (1 paper, 2018). A carcinoma that arises from epithelial cells of the prostate gland. "Notably, they included DMRs close to many genes previously implicated in prostate cancer (e.g., NEAT1, MTOR, RHCG, KCNC2, WT1, HOXC12, KMT2B)." (PMID 30318509, 2018).
renal cell carcinoma (1 paper, 2022). "This study aims to clarify the mechanistic action of long non-coding RNA (lncRNA) SNHG12 in the development of renal cell carcinoma (RCC), which may be associated with promoter methylation modification by KMT2B and the regulation of the E2F1/CEP55 axis." (PMID 35597996, 2022).
sarcoma (1 paper, 2019). A usually aggressive malignant neoplasm of the soft tissue or bone. "The current study showed that, in contrast to the CSC analysis, cfDNA was unable to detect the somatic KMT2B mutation found in the sarcoma." (PMID 31882696, 2019).
schizophrenia (1 paper, 2025). A major psychotic disorder characterized by abnormalities in the perception or expression of reality. "In addition to including members of the Set1-like H3K4 methyltransferase family (Kmt2a, Kmt2b, Kmt2c, and Kmt2d), these modules also encompassed rare variant genes associated with schizophrenia and ASD (Setd1a, Cacna1g, Ank3, Shank1, and Shank3)." (PMID 40102613, 2025).